CCND1 (cyclin D1)
Diseases named in the same sentence as CCND1 in open-access papers (continued):
Sharing a sentence is not in itself a finding about the gene and the disease.
breast cancer (continued). "Because of its positive interactions with cyclin D1 and cyclin E, CEBPD appears to have tumor suppressive functions in breast cancer while being reduced or undetectable in invasive/metastatic cancer and tumor promoters." (PMID 37047552, 2023). "For some known genes related to breast cancer (e.g., MYC, IGFBP5, CCND1, ESR1), we confirmed epithelial cells showed higher expression levels." (PMID 37340002, 2023). "Cyclin D1 is required for the proliferation of mammary epithelial cells during pregnancy, and the knockout of either cyclin D1 or CDK4 prevents the development and growth of mammary carcinomas arising from luminal epithelial cells in mice." (PMID 37835528, 2023). "Likely, lncRNA NEAT1 expression was upregulated in breast cancer tissues, and its inhibition in SKBR3 cells impaired cell proliferation by sponging miR-410-3p and subsequently downregulating cyclin D1 (CCND1)." (PMID 36613528, 2022). "The overexpression of SOD2 in breast cancer MCF-7 cells increased the expression of p21 and E-cadherin and decreased the expression of Cyclin D1 and MMP-2, suggesting that SOD2 inhibits the proliferation, migration, and invasion of MCF-7 cells." (PMID 36142828, 2022). "The genes involved in the known three loci—FGFR2, CCND1 and TOX3—have been thoroughly discussed in relation to breast cancer." (PMID 35267517, 2022). "Cyclin D1, MMP-2, and MMP-9 are upregulated by STAT3-containing exosomes and promote proliferation and invasion of breast cancer cells." (PMID 35765040, 2022). "Mechanistically, there were confirmed binding sites between hsa_circ_0006014 and miR-885-3p, and hsa_circ_0006014 promoted breast cancer cell proliferation partially by sponging miR-885-3p and influenced CDK2/CCNE1 and CDK4/6/CCND1." (PMID 35383130, 2022). "In this study, for the first time, we report five oncogenes (TUBA1B, SLC2A1, PGK1, CCND1, and NCAPD2) and two tumor suppressors’ genes (RPLP2, RPL37) as novel therapeutic targets in breast cancer." (PMID 35622738, 2022). "ERα and ERβ are activated after binding to estrogen, form dimers, and bind to target genes such as CCND1, HIF1A, and IL6, which have a role in breast cancer proliferation." (PMID 36106139, 2022). "To more specifically investigate the beneficial impact of MB basal expression on limiting cancer cell proliferation, we analyzed the expression of cyclin D1 and cyclin E in MCF7 cells, both regulating the cell division process in murine mammary tumors." (PMID 36232784, 2022). "MiR-8073 binds to at least five mRNAs (FOXM1, MBD3, CCND1, KLK10, and CASP2) in various cancers such as colon, pancreatic, and breast cancer in vitro and determines the gene and protein expression levels of these five targets." (PMID 35163589, 2022). "For the first time in this study, we used a comprehensive in silico approach and identified five proto-oncogenes (TUBA1B, SLC2A1, PGK1, CCND1, and NCAPD2) and two tumor suppressor genes (RPLP2, RPL37) as novel therapeutic targets against breast cancer." (PMID 35622738, 2022). "Tamoxifen-resistant breast cancer cells, MCF7 and T47D, have been reported to overexpress cyclin D1 owing to the inhibition of cyclin D1 degradation." (PMID 36359211, 2022). "Isoangustone A dose-dependently decreased DNA synthesis and induced G1 phase arrest in human prostate and mouse breast cancer cells, reduced the levels of CDK2 and CDK4 as well as cyclin A and cyclin D1 proteins, and also induced a decrease in CDK2 activity." (PMID 36278690, 2022). "ER+ breast cancer is highly reliant on an intact cyclin D-CDK4/6-Rb axis, as estrogen drives cyclin D1 expression leading to the formation of the cyclin D-CDK4/6 complex, ultimately inducing cell proliferation through the CDK4/6 pathway." (PMID 36176758, 2022). "Mechanistic analysis indicated that MY11 suppressed the expression of Bcl-2 and Cyclin D1 and induced the expression of PUMA, Bax, p21 and P-p65 in breast cancer cells in vitro and in vivo." (PMID 35759135, 2022).
breast cancer (continued). "When 14-3-3 sigma was overexpressed, Western blot assay presented increased protein expression of P21 and decreased levels of cyclin D1, CDK2 and CDK6 in breast cancer cells." (PMID 35890172, 2022). "In breast cancer, RANKL activates NF-κB, inducing cellular proliferation by targeting cyclin D1 gene." (PMID 36531159, 2022). "Recent large-scale cancer genomic datasets show the overlap between CCND1 amplification and ERBB2 amplification in breast cancer patients." (PMID 35742993, 2022). "Amplification of some oncogenes in breast cancer, especially in the TNBC type, is very common, such as EGFR, E2F, CCND1, Myc, Ras and Notch." (PMID 35892755, 2022). "TUBA1B, SLC2A1, PGK1, CCND1, and NCAPD2 have been overexpressed in breast cancer tissues and their promoter region was hypomethylated (The graph on top shows gene expression and the graph at the bottom shows methylation beta value)." (PMID 35622738, 2022). "It has been reported that cyclin A1 and cyclin D1 were transcriptional targets of SIX1 and that SIX1 promoted cell proliferation in breast cancer by increasing cyclin A1 expression and in pancreatic cancer via increasing cyclin D1 expression." (PMID 35287543, 2022). "Sesaminol, an ingredient of sesame that is cytotoxic towards the MCF7 human mammary carcinoma cell line, is known to bind to ANT2 and reduce the protein expression of cyclin D1, which is important for the G1/S phase transition of the cell cycle." (PMID 35164336, 2022). "In ER+ breast cancer, miR-129 inhibits estrogen receptor 1 (ESR1)-mediated NOTCH signaling in CSC-like cells by suppressing cyclin D1/DICER1 mediated let-7 maturation, leading to increased NUMB expression to repress NOTCH signaling activity." (PMID 34572067, 2021). "Our study showed that levels of WNT/β‐CATENIN target genes CYCLIN D1, c‐MYC and SURVIVIN are elevated in breast cancer cells." (PMID 33462997, 2021). "α-Mangostin induces apoptosis of breast cancer cells through the PI3K/Akt signaling pathway by targeting RXRα, and cyclin D1 has involved in this process." (PMID 34539418, 2021). "CCND1, SKIL and CD46 primarily involved in early breast cancer progression and immune evasion were predicted to be dysregulated by circRNA‐miRNA interaction." (PMID 33544410, 2021). "As FOXA1 governs the estrogen-regulated transcriptome and cell growth in breast cancer, it is unsurprising that FOXA1 is required for estrogen-induced cyclin D1 (CCND1) expression, cell cycle progression, and proliferation of luminal breast cancer." (PMID 34680352, 2021). "The results showed that in breast cancer, the expression of CREPT was positively correlated with Bcl-XL and weakly correlated with c-MYC and CCND1 at the mRNA level." (PMID 33531691, 2021). "α-Mangostin induces apoptosis, suppresses the migration and invasion of breast cancer cells through the PI3K/AKT signaling pathway by targeting RXRα, and cyclin D1 has involved in this process." (PMID 34539418, 2021). "To further characterize the estrogenic response of BSD, we investigated the effect of BSD on the expression of estrogen-regulated genes: c-Myc and Cyclin D1, which are known as estrogen inducible genes, in MCF-7 human breast cancer cells." (PMID 34073781, 2021). "The PGR, ESR1 and CCND1 genes were downregulated when NRIP1 was silenced, indicating the possible role of NRIP1 in breast cancer development." (PMID 34707101, 2021). "Our data showed that YTHDF1 knockdown distinctly lowered the expression of Axin2, c-myc, β-catenin, and cyclin D1 in MCF-7 cells, confirming that YTHDF1 participated in the activation of WNT pathway in breast cancer." (PMID 34434939, 2021).
breast cancer (continued). "In breast cancer cells, the deletion of KDM4B not only reduces the transcription of WEE1, CCND1, and CCNA1, but also disrupts the estrogen-induced cell cycle G1-S phase transition, causing breast cancer cells to stall at the G2-M phase or G1-S phase." (PMID 35186950, 2021). "Low cyclin D1 (CCND1) expression displays increased expression of EMT markers, increased migration of breast cancer cells and drug resistance." (PMID 34123801, 2021). "In breast cancer cells, the decrease in CXCL13 leads to the decreased expression of CXCR5, p-ERK/ERK, and cyclin D1 as well as the increased expression of cleaved Casp-9, which is an initiator caspase protease for apoptosis." (PMID 34947813, 2021). "In breast cancer, an anti-CXCL13 antibody suppressed tumor growth by inhibiting the TGF-β1, IL-1, TNF, cyclin D1, and CXCR5/Erk pathways and repressed tumor metastasis by inhibiting RANKL production." (PMID 34947813, 2021). "CP extract was previously reported to decrease the expression of cyclin D1 and its kinase partner (CDK6) in the hepatoma cell line HepG2 and the breast cancer cell line MCF-7." (PMID 34299510, 2021). "Cyclin D1 is a transcriptional target of ER, and CCND1 amplification is found in 15% of breast cancers." (PMID 33407601, 2021). "Surprisingly, breast cancer SNPs (rs78540526 and rs554219) in PRE1 almost completely abolished enhancer function and decreased the amount of cyclin D1 protein in MCF7 cells." (PMID 35011637, 2021). "Cisplatin drug targets cyclin D1, and treatment of ER-positive MCF-7 breast cancer cells with cisplatin increased cell death or growth arrest by decreasing the cyclin D in MCF-7 cells." (PMID 33920506, 2021). "In detail, ROR2 overexpression promotes PI3K activation and AKT phosphorylation, followed by the downregulation of p21 and upregulation of cyclin D1 and PDK1, resulting in increased proliferation and survival of breast cancer cells." (PMID 34440262, 2021). "Inhibition of mTORC1 activity down-regulated cyclin D1 mRNA and protein levels in MCF7 breast cancer cells, but this effect was rescued when eIF4E activity was enhanced by the knockdown of 4E-BP1." (PMID 34208071, 2021). "In this review, we examine the role of crosstalk between PRLR and ERBB1/2 signaling pathways in the activation of unliganded ERα, cyclin-D1 and other oncogenic factors (MYC, FOS, JUN) in breast cancer." (PMID 34572912, 2021). "For example, cyclin D1 (CCND1), a promoter of the G1/S transition, is overexpressed in estrogen receptor-positive breast cancer cells." (PMID 33686022, 2021). "Further, TNBC cases with a low amount of cyclin D1 expression had higher tumor grade, tumor stage, and more positive lymph nodes with lymphovascular invasion, proposing that cyclin D1 expression may be a key factor to consider for aid in breast cancer management." (PMID 33920506, 2021). "Increased relative gene expression and copy number variation of CCND1 and YWHAZ was observed in MDA-MB-468 breast cancer cells and silencing PGRMC1 reduced the expression of these genes." (PMID 34350123, 2021). "In breast carcinoma cells, under the stimulation of estrogen, PELP1 formed a complex with pRb, which subsequently facilitated CDKs and cyclin D1 induced phosphorylation of pRb, therefore, promoted the progress of cell cycling." (PMID 34257530, 2021). "Elevation of CCND1 and AGR2 mRNA levels were also observed in the ERα (-) breast cancer cells treated with LDN." (PMID 32042339, 2020).
breast cancer (continued). "In pancreatic cancer and breast cancer, ETV4 directly upregulates the transcription of cyclin proteins, such as cyclin D1 and cyclin D3 to promote cell proliferation." (PMID 32018225, 2020). "As high expression levels of Cyclin D1 and CDK4 are frequently found in breast cancer and contribute to uncontrolled proliferation, they are potential candidates for biomarkers." (PMID 33255177, 2020). "We have previously shown that cyclin D1 expression and AKT phosphorylation are markedly reduced in breast cancer cell lines after PLAC1 knockdown." (PMID 32499871, 2020). "A likely explanation is that Sox2 facilitates the G1/S transition of the cell cycle and up-regulates the CCND1 (cyclin D1) gene, as demonstrated in the luminal MCF-7 and triple-negative MDA-MB-231 breast cancer cell lines." (PMID 33553286, 2020). "In contrast, the proliferation marker cyclin D1/2 was even reduced at higher concentrations in all 3 cell lines and CDK4 in the two breast cancer cell lines whereas PCNA levels stayed unaffected." (PMID 32292575, 2020). "For example, in breast cancer cells, the interaction of FLNA with cyclin D1 promotes migration and invasion, while on the other hand, the regulation of focal adhesion disassembly by FLNA leads to the suppression of breast cancer cell migration and invasion." (PMID 32545553, 2020). "Similar conflicting prognostic links between gene expression and tumor protein levels in breast cancer have been reported for the cell cycle regulator CCND1 gene and corresponding cyclin D1 protein, as well as for PD-L1 gene and protein expression." (PMID 32560703, 2020). "Meanwhile, in breast cancer, the heterotopic expression of miR-193a-3p in cancer cells directly targets mitogen-activated protein kinase 8 (MAPK8), resulting in low CCND1 expression levels." (PMID 32095323, 2020). "We also explored the impact of HERV expression in its neighboring breast cancer development genes (BRCA1, CCND1, NBS1/NBN, RAD50, KRAS, PI3K/PIK3CA) and in long non-coding RNA expression (AC060780.1, also known as RP11-242D8.1)." (PMID 33194615, 2020). "Here, we present a list of seven putative genes that are modulated by Rsv in breast cancer in the context of cotreatment with Doxo: HSP90AA1, CCND1, CDH1, ESR1, MAPK3, PTPN11, and RPS6KB1." (PMID 33204396, 2020). "In contrast, the IL-1β/IL-1R1/β-catenin signaling pathway that regulates c-MYC, cyclin D1 (CCDN1), SNAIL1, and matrix metallopeptidases (MMP) 2 expression promotes proliferation, migration, and invasion in breast cancer." (PMID 32397236, 2020). "(A) Representative zoom-in chromosome views of clonal prototypical breast cancer amplicons such as ERBB2 and CCND1 identified in patient samples." (PMID 32401198, 2020). "The results shown that the expression of TRRERF1, PER1, TUFT1, CCND1, and ENPP2 genes was significantly different in breast cancer and adjacent tissues (p < 0.0001)." (PMID 33365308, 2020). "Frequently affected genes by CNVs in Chinese breast cancer patients were ERBB2 (25%), MIEN1 (25%), GRB7 (24%), TRPS1 (6%), MYC (6%), ERLIN2 (6%), PLPP5 (6%), NSD3 (6%), FGFR1 (6%), and CCND1 (5%)." (PMID 33173047, 2020). "A high expression of Cyclin D1 and CDK4 is frequently found in breast cancer and deregulation of this pathway contributes to uncontrolled proliferation in hormone receptor-positive breast cancer." (PMID 33255177, 2020). "LINC00885 silencing in breast cancer lines overexpressing this lncRNA leads to downregulation of proliferation related transcripts such as EREG, CMYC, CCND1 and to significant decrease in cell migration and motility." (PMID 33049922, 2020). "Moreover, CCND1 may mediate FGFR1-induced drug resistance in ER+ breast cancer." (PMID 32380883, 2020). "Collectively, miR-93 promotes apoptosis of breast cancer cells via repressing E2F1 and CCND1, thereby mediating pAKT activity and apoptosis-related proteins." (PMID 32796817, 2020).
breast cancer (continued). "In this subset of genes, we confirmed three genes with established roles in breast cancer, including HES4, CCND1, IGFBP3, with quantitative RT-PCR analyses." (PMID 31462705, 2020). "Further, we found that knockdown RAI14 inhibits the proliferation, migration and invasion of breast cancer cells by regulating cell cycle and EMT through Akt/Cyclin D1, MMP2, MMP9 and ZEB1/E-cadhrin/Vimentin pathway." (PMID 31772666, 2019). "Among the most significant overlaps we found up-regulated gene sets in MCF-7 breast cancer-, and MCF-10 mammary epithelium cell lines, where CCND1, MAP2K1 or EIF4G genes were over-expressed/knockdown, respectively." (PMID 31191821, 2019). "In our present study, the wild and overexpression of STAT3 MDA-MB-468 breast cancer cells were treated with dovitinib for 24 h and cell apoptosis and expression of STAT3/cyclin D1 axis were analyzed subsequently." (PMID 31485222, 2019). "Our unexpected findings contrast with the initial application of CDK4/6 inhibitors in treating ER+ breast cancers that are often characterized with dysregulated CDK4/6 activation, where the oncogenic addiction to cyclin D1 is being targeted." (PMID 30718512, 2019). "The FOSL1,GSTP1 and CCND1 genes are located at11q13, a cytoband commonly affected by CNA in breast cancer, with relevantfunction in progression and invasion." (PMID 30816904, 2019). "The expressions of cyclin D1, TOP2A, and RacGAP1 were found to be slightly up-regulated in the primary breast cancer cell samples treated with E2." (PMID 31293425, 2019). "Re-expression of LINC01355 suppresses the growth and tumorigenesis of breast cancer cells, which involves the stabilization of FOXO3 and enhancement of FOXO3-mediated transrepression of CCND1." (PMID 31243265, 2019). "LINC01355 acts as a tumor suppressor in breast cancer, which is ascribed to enhancement of FOXO3-mediated transcriptional repression of CCND1." (PMID 31243265, 2019). "Cyclin D1 is extensively increased in breast cancer cells, indicating the possible anti-cancer effects of ISO against breast cancer cell lines." (PMID 31817453, 2019). "Some reports have shown that specific gene transcripts within CAFs may be involved in breast cancer cell growth and metastasis, such as the loss of p85α, the Phosphatase and tensin homolog (PTEN), or TGF-receptor type 2 as well as the overexpression of cyclin D1." (PMID 31698786, 2019). "Previous studies have reported a reduction in cyclin D1 levels, and G0/G1 cell cycle stage arrest leads to an increase in migratory activities of MDA-MB-231 breast cancer cells." (PMID 31185953, 2019). "Consistent with the finding that knockdown of FOXO3 abrogates LINC01355-induced downregulation of CCND1, FOXO3 depletion reverses the inhibitory effect of LINC01355 on breast cancer cell proliferation and tumorigenesis." (PMID 31243265, 2019). "PIN1 is overexpressed in breast cancer and mediates its function via RAS signaling, increasing the transcription of c-Jun towards Cyclin D1." (PMID 31083670, 2019). "In breast cancer cells, ERK inactivation is accompanied by the inactivation of cyclin D1 and BCL2, leading to apoptosis." (PMID 31799197, 2019). "This study focused on the role of SIRT4 in the tamoxifen sensitivity of breast cancer and demonstrated that SIRT4 blocks the transcription and translation of MYC and CCND1 in ER‐positive breast cancer, through the STAT3 pathway." (PMID 31573734, 2019). "Ectopic upregulation of miR-34a expression led to partial MDR reversal, reduction of target genes Ccnd1, Notch1 and BCL2 expression and increased apoptotic rates in MDR breast cancer cells." (PMID 35582270, 2019).